CCR6 (C-C motif chemokine receptor 6)
Diseases named in the same sentence as CCR6 in open-access papers (continued):
Sharing a sentence is not in itself a finding about the gene and the disease.
Crohn disease (13 papers, 2010 to 2022). A gastrointestinal disorder characterized by chronic inflammation involving all layers of the intestinal wall, noncaseating granulomas affecting the intestinal wall and regional lymph nodes, and transmural fibrosis. "Genome-wide association studies have revealed that IL23R and five additional genes involved in Th17 differentiation (IL12B, JAK2, STAT3, CCR6 and TNFSF15) are associated with susceptibility to Crohn’s disease." (PMID 36498596, 2022). "A CXCR3+CCR6+ Th subpopulation that rivals with Th1 in INFγ production has been recently described as Th17.1 and identified in sarcoidosis and Crohn’s disease." (PMID 28289412, 2017). "CCL20 and CCR6 mRNA abundances were increased during active inflammation (CCL20 5.4-fold in ulcerative colitis and 4.2-fold in Crohn’s disease; CCR6 1.8 and 2.0, respectively)." (PMID 26536229, 2015). "Previously, cloned CCR6+ cells from peripheral blood and inflammatory sites in Crohn's disease have been shown to produce IL-17." (PMID 22490506, 2012). "Notably, in Crohn’s disease Th17.1 cells, one of the subpopulations within CCR6+ memTh cells, are the most GC-resistant cells." (PMID 30236152, 2018).
lupus (13 papers, 2010 to 2023). "Our data offer a scientific rationale for exploring the utility of Th17 cells, as well as Th17-associated molecules CCR4 and CCR6 as biologic markers for disease activity in human lupus." (PMID 20334681, 2010). "And then there are the potent TPH cells with TFH like phenotype but are CXCR5-; they help lupus B cells also by producing IL-21; and IL-10–producing CCR6+T cells populate lymph nodes of SLE patients." (PMID 33936042, 2021). "We noticed a strong correlation between the frequencies of CD4+IL-17+ T cells and CD4+CCR4+CCR6+ T cells in the peripheral blood of lupus patients." (PMID 20334681, 2010). "Among the surface molecules, the expression of CD55, CD86, CD93, and CCR6 were decreased in G-MDSCs from pristane-induce lupus mice, and INK128 could increase the expression of these genes." (PMID 34282122, 2021). "This co-relational analysis emphasized that CCR6+ Th22 cells might play a pertinent role in the pathogenesis of lupus involving skin issues." (PMID 29021537, 2017). "Of interest, CD4+CCR4+CCR6- T cells also appeared to expand in active lupus patients." (PMID 20334681, 2010). "Higher percentages of CCR6+ T helper cells have been found in patients with systemic lupus erythematosus (SLE), especially in lupus nephritis." (PMID 37092451, 2023). "CCR6 was seen to be overexpressed in the B cells of patients with systemic lupus erythematosus (SLE)." (PMID 35634297, 2022). "Further correlation analysis of cytokines in SLE patients with sole lupus skin disease revealed that plasma IL-22 levels correlated positively with the percentage of CCR6+ Th22 cell population (P = 0.0159, r = 0.5314), and the SI (P = 0.0107, r = 0.5570)." (PMID 29021537, 2017). "In NZB/W F1 mice, the expression of CCR6 and CCL20 is increased in the kidney with lupus development." (PMID 27403037, 2016). "The analysis of peripheral blood B cells by flow cytometry showed that the surface expression of CXCR4 was up-regulated on the surface of B cells of lupus mice, whereas there was no detectable change in the surface expression of CCR6, CCR7 and CXCR5." (PMID 25909640, 2015). "In a representative experiment, we found that, unlike CCR6, CCR7 and CXCR5, the surface expression of CXCR4 was substantially up-regulated on the surface of B cells of lupus mice compared with the control non-lupus mice." (PMID 25909640, 2015).
asthma (12 papers, 2011 to 2026). "In murine models, CCR6 deficiency or IL-23 blockade reduced cigarette smoke–induced emphysema, whereas anti-IL-23 treatment in severe asthma patients worsened outcomes, highlighting the complex role of the Th17 axis in airway disease." (PMID 41164185, 2025). "Logistic regression analysis further indicated that CD4+CCR6+CRTh2+ memory Th2 cells and wheezing frequency were the independent risk factor for the outcome of asthma diagnosis." (PMID 34090369, 2021). "As compared to loose API, circulation CD4+CCR6+CRTh2+ memory Th2 cells had better efficiency in predicting risk of asthma diagnosis based on higher specificity, higher PPV and larger area under the ROC curve." (PMID 34090369, 2021). "Our exploratory study shown that circulating CD4+CCR6+CRTh2+ memory Th2 cells increased in asthma diagnosed children and it was a high-risk factor for asthma." (PMID 34090369, 2021). "CD4+CRTH2+CCR6+ cells secrete IL-17, IL-4 and IL-13, leading to the infiltration neutrophils and eosinophils, which is responsible for chronic inflammation associated with asthma." (PMID 34090369, 2021). "Finally, among genes involved in cGVHD susceptibility identified in previous SNP association studies it is notable that CCR6 can induce phosphorylation of STAT3 in asthma and that STAT3 is an important binding partner of FGDR1 in the development of non-small cell lung cancer." (PMID 37731134, 2023). "Moreover, circulation CD4+CCR6+CRTh2+ memory Th2 cells, which have certain lung tissue specificity, was increased in asthma diagnosed children and was risk factor for the outcome of asthma diagnosis." (PMID 34090369, 2021). "CCR6+ Treg cells are the major proinflammatory Treg population that responds to HDM in human asthma exacerbations." (PMID 34497608, 2021). "Logistic regression analysis indicated that circulating CD4+CCR6+CRTh2+ cells (EXP, 8.986; 95 % CI,1.886–42.816) and wheezing frequency(EXP, 0.127; 95 % CI, 0.023–0.703)were high risk factors for asthma." (PMID 34090369, 2021). "Statistical methods were used to determine the correlation between the level of circulating CD4+CCR6+CRTh2+ memory Th2 cells and a diagnosis of asthma, thereby providing a theoretical basis for the early diagnosis of asthma in children." (PMID 34090369, 2021). "We calculated NPV and PPV for API and CD4+CCR6+CRTH2+ memory Th2 cells level in predicting asthma diagnosis." (PMID 34090369, 2021). "Detecting of CD4+CCR6+CRTh2+ memory Th2 cells in BALF would be more valuable in predict future asthma since those cells are mainly resident in airway." (PMID 34090369, 2021). "We found that the level of CD4+CCR6+CRTh2+ memory Th2 cells in the asthma diagnosed group was significantly higher than those in the non-asthma diagnosed group." (PMID 34090369, 2021). "Collectively, these findings suggest that CCR6+ Treg cells trafficking via CCL20, may be associated with the pathology of asthma." (PMID 34497608, 2021). "Since the airway responsiveness was relieved in CCR6-deficient mice, CCL20-CCR6 axis could be a putative approach for the asthma therapy." (PMID 32582180, 2020). "The fact that CCR6 is overexpressed in untreated asthma patients seems to be especially interesting, since CCR6 has been shown to target lymphocytes to the lungs, and might thus be a sign for poorly controlled asthma." (PMID 26953825, 2016). "Therefore, increasement of circulating CD4+CRTH2+CCR6+ memory Th2 cells may reflect the chronic airway allergic inflammation, an important immunological feature of asthma." (PMID 34090369, 2021). "In addition, the proportion of circulating CD4+CCR6+CRTh2+ memory Th2 cells were measured, and the wheezing children were followed up for 2 years to confirm whether they were diagnosed with asthma." (PMID 34090369, 2021). "The results indicated that circulation CD4+CCR6+CRTh2+ memory Th2 cells displayed higher specificity and PPV in predicting asthma diagnosis." (PMID 34090369, 2021).
asthma (continued). "The marker CD196 also called chemokine receptor 6 (CCR6), and its ligand CCL20, contributes to the recruitment of Th17 cells and Th2 cells to the injured tissue and specially deal with the asthma exacerbation." (PMID 32582180, 2020). "In the mouse model of asthma, the CCL20/CCR6 system plays a pivotal role in allergic airway responses such as airway resistance, airway eosinophilia, and production of IL-5 and IgE." (PMID 22013453, 2011). "Most allergic participants' responsive T cells had a C‐C chemokine receptor type 4 (CCR4) (+) phenotype, with a subset expressing CCR4(+) CCR6(+), regardless of asthma status." (PMID 41179368, 2025). "The mean of circulating CD4+CCR6+CRTh2+cells in children diagnosed with or without asthma was 1.6 %±0.8 and 0.8 %±0.6 %, respectively, and was significantly higher in children diagnosed with asthma (p < 0.01)." (PMID 34090369, 2021). "We found that there were significant differences in wheezing frequency,level of CD4+CCR6+CRTh2+ memory Th2 cells and API between children diagnosed with asthma and children with non-asthma outcomes." (PMID 34090369, 2021).
pancreatic cancer (12 papers, 2010 to 2025). "The results of this manuscript show that CCL20 and its corresponding receptor CCR6 are significantly up-regulated in patients with pancreatic cancer (PCA) and that CCL20 is significantly associated with advanced T-category in those patients." (PMID 20459729, 2010). "CC-chemokine receptor 6 (CCR6) acts as a receptor for CCL20 in pancreatic cancer cells, mediating the promotion of pancreatic cancer growth and liver metastasis by CCL20 in a mouse model." (PMID 40034694, 2025). "One study has shown that co-culturing with M2-type macrophages has enhanced the invasiveness of pancreatic cancer cell lines, whereas transfection with CCR6 RNA interference has significantly reduced the invasiveness of the cell lines." (PMID 32707869, 2020). "The overexpression of MMP9 induced via the interaction of macrophage inflammatory protein-3 alpha (MIP-3α) with its receptor, increases the expression of CCR6 on pancreatic cancer cells, consequently increasing the invasion of pancreatic cancer cells." (PMID 30987642, 2019). "It was previously showed that both pancreatic cancer cells and tumor-associated macrophages are in vivo sources of CCL20 mRNA, and CRC cell lines expressed transcripts for both CCL20 and its receptor CCR6." (PMID 24979261, 2014). "To speculate, the CCR6 high PDCs in our system might migrate into the CCL20 positive pancreatic tumor microenvironment." (PMID 20976171, 2010). "In pancreatic cancer, CD25+CCR6+ Th17 cells showed a stronger suppressive effect than the CD25-CCR6- Th17 phenotype." (PMID 32488850, 2020). "MIP-3α, through its receptor CCR6, induce expression of MMP9 in pancreatic cells and thereby increase pancreatic cancer cell invasion through collagen Type IV." (PMID 30925924, 2019). "CCR6 is also the receptor for the chemokine CCL20 which is produced by M2 macrophage, and mediates the effect of CCL20 on EMT and cell invasion of pancreatic cancer cells." (PMID 30925924, 2019). "We measured CCR2, CCR5, CCR6, and CCR7, on DCs before and after surgical removal of the pancreatic tumor mass." (PMID 20976171, 2010). "Moreover, expression of the CCL20/CCR6 system has been reported in PCA tissues and pancreatic cancer cell lines." (PMID 20459729, 2010).
cervical cancer (11 papers, 2015 to 2025). A primary or metastatic malignant neoplasm involving the cervix. "The chemokines controlling lymphocyte trafficking to HPV skin are under investigation with one report suggesting that Th17 cells infiltrate human cervical cancer via CCR6/CCL20 interactions." (PMID 28523003, 2017). "All these results, together with our data, show Th17 cell-expressed CCR6 is functional and play an important role in the development of cervical cancer." (PMID 25768730, 2015). "Second, the circulating Th17 from patients with cervical cancer highly expressed CCR6, and selectively migrate in response to CCL20 in vitro." (PMID 25768730, 2015). "Moreover, one study has shown that CCL20 chemoattracts Th17 in vitro, while Th17, highly expressing CCR6, is significantly accumulated in cervical cancer tissue." (PMID 32707869, 2020). "Consequently, to our knowledge the functional association of receptors including CCR6, EPHB2, NR2C1, and NR2C2 with cervical cancer is being proposed for the first time in this study." (PMID 30020984, 2018). "In cervical cancer, CCL20 modulates immune cell infiltration through its receptor CCR6, promoting tumor progression." (PMID 40517358, 2025). "Th17 cells can be recruited to the TIME via the CCR6-CCL20 pathway in cervical cancer due to upregulated CCL20 in tumor tissues and high expression of CCR6 on Th17 cells aggregated within tumor tissues." (PMID 33868269, 2021). "This implies that AEG is an important component of the CCL20/CCR6-Erk1/2-Akt-EMT pathway and could be a novel targeted therapy for cervical cancer." (PMID 36766756, 2023). "Moreover, in cervical cancer, increasing CD45RA+/CD45RO+ and decreasing CCL20+/CCR6+ expression correlated with neoplasia severity." (PMID 35805132, 2022). "Furthermore, cervical cancer cells instruct primary cervical fibroblasts to produce high levels of CCL20 and to attract CD4+IL17+CCR6+ cells." (PMID 32707869, 2020).
ulcerative colitis (10 papers, 2010 to 2023). An inflammatory bowel disease involving the mucosal surface of the large intestine and rectum. "The present study aimed to clarify whether the expression of CCL20 and its receptor, CCR6, was correlated with the development of ulcerative colitis (UC)-associated neoplasia." (PMID 24179507, 2013). "In contrast, cDC2 in aUC patients displayed lower expression levels of both CCR2 and CCR6 compared to those in quiescent ulcerative colitis (qUC) patients." (PMID 37893204, 2023). "The aim of this study is to clarify the differences of CCL20 and CCR6 expression, chemokine correlated to intestinal homeostasis, between pediatric and adult ulcerative colitis (UC) patients." (PMID 25691899, 2015). "Interestingly, in the setting of human ulcerative colitis, expression levels of Hedgehog components positively correlated with the expression levels of key Th17 markers such as IL17A and CCR6." (PMID 35835905, 2022).
glioma (9 papers, 2015 to 2023). A benign or malignant brain and spinal cord tumor that arises from glial cells (astrocytes, oligodendrocytes, ependymal cells). "As the sole cytokines incorporated into the construction of GA-MSCRGPI, C–C motif chemokine ligand 20 (CCL20) encodes a ligand for the C–C chemokine receptor CCR6 involved in immunomodulation of glioma cells." (PMID 37005685, 2023). "Consistently, patients with high levels of ADO were usually accompanied by an overexpression of CCL20 and its only known receptor CCR627,28, whereas low ADO expression was associated with low levels of CCL20 and CCR6 in gliomas." (PMID 33483477, 2021). "Finally, a co-culture model of glioma cells with normal astrocytes suggests that astrocyte-mediated production of CCL20 facilitates CCR6-expressing GBM cell adaptation to hypoxic TME via upregulation of hypoxia-inducible factor 1-alpha (HIF1-α)." (PMID 35008294, 2021). "Lymphocyte infiltrates expressed CXCR3/6 and CCR6, but the CXCR3 ligands CXCL9/10/11 were rarely detected in glioma samples with the exception of interferon-activated microglia." (PMID 34692159, 2020). "In fact, in a glioma model, it has been shown that CCL20 [chemokine C-C motif ligand 20) is released by astrocytes in response to hypoxia and, by stimulating the CCR6-NF-κB signaling pathway, further enhances the HIF-1-mediated hypoxic response." (PMID 33066172, 2020). "In glioma tissues, CCL20 and its receptor, CCR6 protein levels are upregulated, compared with their expression in non-neoplastic brain tissues." (PMID 29212174, 2017).
ovarian carcinoma (9 papers, 2010 to 2024). A malignant neoplasm originating from the surface ovarian epithelium. "Cisplatin-stimulated classically activated macrophages promote ovarian cancer cell migration by increasing CCL20 production, which activates its receptor CCR6 on ovarian cancer cells, triggering EMT." (PMID 32707869, 2020). "In vitro, cisplatin stimulated human macrophage-like THP-1 to become classically activated (CAMs) and to produce CCL20, chemokine ligand 20 (macrophage inflammatory protein-3 (MIP3A), that activates CCR6 on ovarian cancer cells, promoting EMT and migration." (PMID 33194645, 2020). "Pharmacological blockage of CCL20 on cisplatin-stimulated activated macrophages and siRNA-mediated inactivation of CCR6 on cancer cells effectively abrogate ovarian cancer cell migration induced by cisplatin-stimulated activated macrophages." (PMID 32707869, 2020). "In clinical ovarian cancer samples, high CCR6 expression on ovarian cancer cells positively correlates with cancer metastasis, leading to poor prognosis." (PMID 32707869, 2020). "In ovarian cancer, cisplatin-stimulated macrophages increase the production of CCL20 and activate the expression of CCR6 on cancer cells, which promotes cell migration." (PMID 35841069, 2022). "CCR6 is overexpressed by liver metastases of ovarian carcinomas, suggesting CCL20-CCR6 interactions promote malignant cancer cells to metastasize to the liver." (PMID 20649989, 2010).
prostate carcinoma (9 papers, 2009 to 2025). A carcinoma that arises from epithelial cells of the prostate gland. "Expression levels of CCR6 in prostate cancer are associated with clinical and pathologic features of more advanced and aggressive prostate cancer status, such as local tumor volume, Gleason score, and lymph node metastasis." (PMID 32707869, 2020). "In support of our findings it was recently published that the expression levels of CCR6 in prostate cancer are associated with clinical and pathologic features of more advanced and aggressive prostate cancer." (PMID 19340288, 2009). "In addition to CXCL12, other studies have also implicated cytokine CCL20 and its receptor CCR6 for their involvement in prostate cancer bone metastasis." (PMID 36836690, 2023). "It has been reported that CCR6 knockout mice had a better survival rate of bone cancer metastasized from prostate cancer." (PMID 36836690, 2023). "Of note, CCR6 knockout mice that had bone cancer metastasized from prostate cancer also possessed higher numbers of CD8+ cytotoxic T lymphocytes." (PMID 36836690, 2023). "Similarly, prostate normal epithelial cellsproduce the chemokine CCL20 and the expression of its receptor(CCR6) in prostate cancer cells has been recently found tobe a predictor of tumour aggressiveness." (PMID 21479216, 2011). "Furthermore, we found that CXCR4, CCL20 and CCR6 are over- and coexpressed in human prostate cancer specimens." (PMID 19340288, 2009). "In a prostate cancer study, tumor cells can induce TAM infiltration and M2 polarization via the CCL20/CCR6 axis, leading to tumor progression." (PMID 38600588, 2024). "To better understand the role of CCL20 in prostate cancer development, we characterized the expression of CCL20 and its receptor CCR6 in human prostate cell lines PC3, LNCaP, 22RV1 and DU145." (PMID 19340288, 2009).